B4GALT5 (beta-1,4-galactosyltransferase 5)
Diseases named in the same sentence as B4GALT5 in open-access papers (continued):
Sharing a sentence is not in itself a finding about the gene and the disease.
prostate carcinoma (1 paper, 2020). A carcinoma that arises from epithelial cells of the prostate gland. "In contrast, mRNA expression of enzymes involved in the biosynthesis of glycosphingolipids, including glucosylceramide synthase (UCGC), and lactosylceramide synthases B4GALT5 and B4GALT6, were elevated in CAV1-high prostate cancer cell lines and prostate tumors." (PMID 32855410, 2020).
cancer (9 papers, 2018 to 2025). A tumor composed of atypical neoplastic, often pleomorphic cells that invade other tissues. "B4GALT5 is an enzyme, and it is associated with malignant tumors." (PMID 37240761, 2023). "B4GALT5 has been associated with cancer progression and drug resistance, especially in gliomas." (PMID 30442960, 2018). "UGCG and B4GALT5, which encodes LCS, were significantly elevated in KRAS mutant cancers (n = ~730), and combined high expression of UGCG and B4GALT5 correlated with shortened 5-year survival." (PMID 36709325, 2023). "Previous research has shown that B4GALT5 is regulated by Ets family transcription factors, including Ets-1 and Ets-2, in cancer cells." (PMID 37628686, 2023). "Concordantly, we found increased B4GALT5 transcripts in human KRAS mutant cancers and elevated LacCer levels in cells expressing KRASG12V." (PMID 36709325, 2023). "In particular, the genes B4GALT5 and GSDMD, which harbour three of the most significant variants, are closely related to cancer progression and the elevation of CA19-9 levels." (PMID 34071263, 2021). "It has been reported that B4GALT5 can suppress apoptosis and enhance cancer cell proliferation." (PMID 35071226, 2021). "Recently, an alternative approach was followed in which the glycosyltransferases ST3GAL2, ST3GAL3, B4GALT5, and B3GALT4 were suggested as a further predictor in identifying GD2-positive phenotypes in cancer patients." (PMID 36551537, 2022).
tumor (9 papers, 2018 to 2025). "RT-qPCR of both in vitro and in vivo tumor cells also revealed significant up-regulation of key enzymes involved in glycosphingolipid biosynthesis, including St3gal1, St3gal2, B4galt5, Sptlc2, and Ugcg, in A159V-mutated cells." (PMID 41160695, 2025). "We also conducted immune infiltration level analysis and confirmed the association of B4GALT5 with tumor immune microenvironment in HCC." (PMID 35410157, 2022). "As B4Galt5 has the potential to promote tumor growth, tumor illnesses are the main focus of current research." (PMID 37658291, 2023). "Consistently, this also showed that the expression of B4GALT5 was higher in tumor samples than in normal samples, suggesting its close relation with HCC." (PMID 35410157, 2022). "B4GALT5 and IDH1 are associated with tumour growth and RASSF3 is a tumour suppressor gene." (PMID 36765842, 2023). "Similarly, deletion of LCS (B4GALT5), or GM3 synthase (ST3GAL5) markedly reduced the growth of MIA PaCa-2 xenografts, as evident by reductions in tumor weight and size." (PMID 36709325, 2023). "ST8SIA4, B4GALT5, and CSGALNACT2 were found to be downregulated in Fra-2 cl 2 scid primary tumours." (PMID 34693476, 2022). "B4GALT5, also known as β-1, 4 galactosyltransferase V, is one of the members of β-1, 4 galactosyltransferase gene (B4GALT) family, which was concerned with embryonic development, tumor generation, other malignant diseases." (PMID 29546034, 2018).
infection (6 papers, 2017 to 2024). The state of being infected such as from the introduction of a foreign agent such as serum, vaccine, antigenic substance or organism. "The reason is probably that UGCG was overexpressed upon infection compared with β4Galt5 and β4Galt6, the two LacCer synthases responsible for the conversion of GlcCer to LacCer." (PMID 38300320, 2024). "More investigations are needed to fully determine the role of GlcCer accumulation and LacCer down-regulation on SFTSV infection, and the role that B4GALT5/6 inhibition plays on the cellular homeostasis of GSL formation." (PMID 28388693, 2017). "Surprisingly, infection with SV40 was also increased when B4GALT5 or B4GALT6 was inhibited, even though GM1a synthesis is downstream of LacCer synthesis." (PMID 28388693, 2017). "The other site (17:51259503-) is located in front of the (310 bp) gene Beta-1,4-Galactosyltransferase 5 (B4GALT5), which has immunological regulation roles in porcine reproductive and respiratory syndrome virus (PRRSV) infection." (PMID 37175634, 2023). "In addition, B4GALT5 up-regulated the expression of chemokines (MCP-1) and receptor (CCR2), which attract more cells to migrate to the site of infection." (PMID 29546034, 2018).
heart disease (1 paper, 2023). "Studies on the role of lactosylceramide in the heart suggest that B4Galt5 may play a significant role in heart disease." (PMID 37658291, 2023).
B4GALT5 also shares sentences with these, for which no sentence is quoted: cervical cancer (2 papers); astrocytoma (1); autoimmune thyroid disease (1); childhood asthma (1); Glucose intolerance (1); heart (1); heart failure (1); hypertrophy (1); leukemia (1); liver cancer (1); lymphoma (1); Myocardial fibrosis (1); primary immunodeficiency (1); prostate tumors (1); type 2 diabetes (1).